GBA1 (glucosylceramidase beta 1)
Diseases named in the same sentence as GBA1 in open-access papers (continued):
Sharing a sentence is not in itself a finding about the gene and the disease.
Parkinson disease (continued). "Parkinson’s disease patient derived neurons harboring mutant GBA1 exhibited prolonged mitochondria-lysosome contacts due to defective modulation of the untethering protein TBC1D15, which mediates Rab7 GTP hydrolysis for contact untethering." (PMID 33753743, 2021). "GBA1 mutations are a risk factor for the development of DLB, suggesting some correlations among GBA1, dementia and parkinsonism." (PMID 33446243, 2021). "With the inclusion of GBA1 in many Parkinson disease NGS analyses, it is important to consider the effects of the nearby homologous pseudogene." (PMID 34234814, 2021). "Three of the seven patients with Parkinson disease were homozygous for N370S; of the other four, one was homozygous for R463C, two were N370S/L444P and one had the L444P/R463C compound GBA1 genotype." (PMID 34649574, 2021). "The objective of this study was to assess the entire GBA1 gene in Parkinson's disease from a single large population." (PMID 32618053, 2020). "The GBA1 gene was assessed in 3402 Dutch Parkinson's disease patients using next‐generation sequencing." (PMID 32618053, 2020). "Mutations in genes for both proteins (GBA1 and LRRK2) are associated with familial cases of Parkinson’s disease." (PMID 30654525, 2019). "The link between GBA1 and parkinsonism was surprising, and only recognized because of clinical findings that led to this association between a rare and common disorder." (PMID 31464647, 2019). "It is possible that lysosomal Ca2+ levels were depleted in GBA1-Parkinson's due to excessive TPC2 activity, however this has yet to be established." (PMID 29746898, 2018). "In order to study the neuropathology and the role of GBA1 in parkinsonism, GD iPSCs have also been differentiated into neurons." (PMID 28592657, 2017). "The discovery of this link between GBA1 and Parkinson's disease has played a large part in a recent explosion of GD research." (PMID 28592657, 2017). "The pathology of Parkinson-GBA1 is identical to that for idiopathic Parkinson’s disease, with the loss of dopaminergic neurons in the substantia nigra and the presence of Lewy bodies and neurites containing alpha-synuclein." (PMID 28969384, 2017). "Although we cannot exclude that due to the long duration of Parkinson-GBA1 in human subjects the cumulative effects of the small increase of endogenous alpha-synuclein can reach a threshold value at which pathological changes are triggered." (PMID 28969384, 2017). "Glucocerebrosidase (GBA1) gene mutations increase the risk of Parkinson disease (PD)." (PMID 27378698, 2016). "Parkinson disease (PD) is the second most common neurodegenerative disorder after Alzheimer disease, whereas Gaucher disease (GD) is the most frequent lysosomal storage disorder caused by homozygous mutations in the glucocerebrosidase (GBA1) gene." (PMID 26860875, 2016). "Despite the increased disease risk posed by GBA1 variants, not all GD patients will go on to develop clinical features of Parkinson disease." (PMID 39822020, 2025). "Overall, the integrated genetic, transcriptomic, and metabolic evidence links defined molecular perturbations to plausible treatment avenues, providing a mechanistic bridge between pathophysiology and therapeutic development in both GBA1-related and sporadic Parkinson’s disease." (PMID 41301891, 2025). "In addition to these, we analyzed the presence of mutations in the GBA1 and FBXO7 genes: the former is included as one of the major risk factors for PD while the latter is linked to an atypical form of parkinsonism." (PMID 40141040, 2025). "Within this group, sphingolipidoses genes involved in glycosphingolipid breakdown are known (GBA1) or candidate (SMPD1, ASAH1) risk factors for Parkinson’s Disease, though disease mechanisms remain unclear." (PMID 41279717, 2025).
Parkinson disease (continued). "We investigated five CSF d18:1 sphingolipid species in a longitudinal multicenter cohort comprising people with Parkinson’s Disease and Dementia with Lewy bodies with and without GBA1 variants and healthy controls." (PMID 39448669, 2024). "It should be noted that we only performed whole-gene GBA1 screening and did not screen for other Parkinson’s disease-related mutations in this study." (PMID 37748026, 2024). "In one of the biggest aggregated PD-focused datasets, researchers found that Parkinson’s disease and dementia with Lewy bodies (DLB) patients with GBA1 variants often also carry a substantial number of other PD-associated risk variants, which can modify the age of onset." (PMID 38153678, 2024). "GBA1 hydrolyzes glucosylceramide into ceramide and glucose in lysosomes, and a recent study showed that CTSB is activated by ceramides to promote PSAP cleavage to saposin C, a coactivator of GBA1 in lysosomes, and that this process is altered in Parkinson disease." (PMID 38911600, 2024). "With disease-modifying treatment for Parkinson’s disease (PD) associated with variants in the glucocerebrosidase gene (GBA1) under way, the challenge to design clinical trials with non-PD-manifest GBA mutation carriers (GBA1NMC) comes within close reach." (PMID 38649346, 2024). "Extensive genotyping for known pathogenic mutations in other monogenic Parkinson's disease genes and any variants of GBA1 associated with increased risk of Parkinson's disease was otherwise negative." (PMID 38059801, 2024). "This study demonstrates evidence of deficits in cortical cholinergic innervation in de novo Parkinson’s disease, with and without GBA1 mutations." (PMID 37748026, 2024). "Variants in seven genes (LRRK2, GBA1, PRKN, SNCA, PINK1, PARK7 and VPS35) have been formally adjudicated as causal contributors to Parkinson’s disease; however, individuals with Parkinson’s disease are often unaware of their genetic status since clinical testing is infrequently offered." (PMID 39074992, 2024). "Recently, GBA1 E326K variant, which has been observed in individuals with Parkinson’s disease (PD) but not Gaucher disease (GD), has emerged as a significant risk factor for DLB1,13–16." (PMID 37745332, 2024). "Although the two Parkinson’s disease groups were not distinguishable by clinical features, GBA1 mutation carriers showed more extensive cholinergic denervation—involving more temporo-parietal regions—than non-carriers compared to healthy controls." (PMID 37748026, 2024). "We investigated clinical features and regional cholinergic terminal changes in de novo Parkinson’s disease subjects with and without relevant GBA1 mutations." (PMID 37748026, 2024). "Combining FDG-PET and 11C-2β-carbomethoxy-3β-(4-fluorophenyl) tropane (CFT), cerebral metabolism and dopaminergic neuronal activity were assessed in N = 6 GBA1 mutation carriers with and without Parkinsonism." (PMID 37626568, 2023). "Although GD is a recessive disease and carriers of GBA1 mutations do not exhibit clinical symptoms, individuals with mono- and bi-allelic GBA1 mutations are at similarly increased risk for development of Parkinson’s disease (PD)." (PMID 36752535, 2023). "The purpose of this study was to assess olfactory function longitudinally in individuals with and without parkinsonism who carry at least one GBA1 mutation." (PMID 36330429, 2022). "On the other hand, only approximately 3% of Asian IPD patients with no apparent family history of parkinsonism are GBA1 mutation carriers." (PMID 36525454, 2022). "However, relying on such panels can miss other mutant alleles, as demonstrated by a 2019 study that fully sequenced GBA1 in an Ashkenazi Jewish Parkinson disease patient cohort." (PMID 34234814, 2021). "Regardless of degree of GCase deficiency, patients with GBA1-associated Parkinson disease appear to have increased α-synuclein aggregation." (PMID 31464647, 2019).
Parkinson disease (continued). "In fact, brain autopsy studies have shown that even some cases of idiopathic Parkinson disease (without GBA1 mutations) exhibit decreased levels of GCase." (PMID 31464647, 2019). "This can be accomplished by performing whole exome or genome sequencing of cohorts with Parkinson disease with and without GBA1 mutations to see if those with GBA1 mutations share other specific variants." (PMID 31464647, 2019). "In the Parkinson’s disease patients, GCase activity was significantly reduced in monocytes, but not lymphocytes, compared to controls, even when GBA1 mutation carriers were excluded." (PMID 30337601, 2018). "GCase activity is significantly decreased in different brain regions in Parkinson-GBA1 patients." (PMID 28969384, 2017). "Parkinson-GBA1 brains might also undergo additional genetic or epigenetic changes to produce Parkinson’s disease." (PMID 28969384, 2017). "Together these results suggest that GBA1 mutations alone are not sufficient to cause overt Parkinson-like pathology, but that additional factors, such as overexpression of alpha-synuclein, are required for this pathology to develop." (PMID 28969384, 2017). "Our results here suggest that GBA1 mutations alone are not sufficient to cause Parkinson’s disease, but also require an additional factor such as increased expression of alpha-synuclein (via, for example, epigenetic modifications)." (PMID 28969384, 2017). "It must be emphasized the vast majority of patients with GD and GBA1 mutation carriers will never develop Parkinson’s disease." (PMID 28933363, 2017). "This can be further explored by comparison of genetic, epigenetic and environmental factors in aged GBA1 mutation positive individuals with and without Parkinson’s disease." (PMID 28969384, 2017). "In this family, comprehensive clinical information, including a post-mortem neuropathology examination, confirmed that HT707 had no indication of parkinsonism, despite harboring biallelic GBA1 mutations resulting in low expression of GCase in in vitro DA neurons, unlike her affected sister." (PMID 38529501, 2024). "In addition, I will discuss how these models fare with respect to the features of a “gold standard” animal models and what could be attempted in future studies to exploit LRRK2 and GBA1 rodent models in the fight against Parkinson’s disease." (PMID 36085537, 2023). "In particular, we envisage that more detailed investigations on experimental models of GBA1-, SYNJ1-, SYPH1-, TMEM230-, Parkin-, PINK1-, ATP13A2-, FBXO7- and SYT11-associated parkinsonism could provide new insight into the pathophysiological mechanisms leading to PD that may involve Rab dysfunction." (PMID 36009486, 2022). "While no published epigenetic studies of Gaucher-associated Parkinson disease exist to date, they may provide insight as to how siblings with the same GBA1 genotype may develop discordant parkinsonian phenotypes." (PMID 31464647, 2019). "However, the majority of patients with GBA1 mutations never develop parkinsonism, so clearly other risk factors play a role." (PMID 31464647, 2019). "However, reduced GCase activity is also found in brain tissue from Parkinson’s disease patients without GBA1 mutations, implicating GCase dysfunction in the more common idiopathic form of Parkinson’s disease." (PMID 30337601, 2018). "Moreover, significant reduction in GCase activity and protein levels is also observed in the brains of Parkinson’s disease patients without GBA1 mutations, indicating the potential importance of GCase in the development of idiopathic Parkinson’s disease." (PMID 28969384, 2017). "In addition to TH, Iba1 and GFAP immunohistochemistry, a range of different proteins involved in processes that may be impaired in Parkinson-GBA1 (such as autophagy, lysosomal functioning and endoplasmic reticulum stress) were analysed by western blotting." (PMID 28969384, 2017).
Parkinson disease (continued). "The most common known disease-associated GBA1 variants in the Ashkenazi Jewish and European populations, p.Asn409Ser, p.Leu483Pro, p.Thr408Met and p.Glu365Lys, were not identified among the screened Parkinson's disease cases of African and African admixed ancestry." (PMID 41058593, 2026). "The primary search terms included “glucocerebrosidase”, “GBA”, “GBA1”, “Parkinson’s disease”, “deep brain stimulation”, “DBS”, and “subthalamic nucleus”." (PMID 41595489, 2026). "There is substantial evidence for a continuum of risk, quantified as altered odds ratio for disease, for several of the genes involved in monogenic Parkinson's disease, such as SNCA, LRRK2 and GBA1 (all with direct or close links to the endo-lysosomal system)." (PMID 38368938, 2024). "AAV-mediated delivery of GBA1, otherwise known as AAV-GBA1, has been tested in animal models to assess its effect on Gaucher and/or Parkinson biomarker levels." (PMID 31464647, 2019). "While GBA1 mutant mice alone often show only modest α-synuclein increases without overt Parkinsonism, combined models robustly reproduce cardinal PD features, including Lewy-type inclusions, TH+ fiber loss, and behavioral deficits." (PMID 41465340, 2025). "Lyso-Gb1 levels, median (range), were 5 (2.7–10.7) in heterozygous GBA1 carriers with Parkinson’s disease (PD), similar to lyso-Gb1 levels in subjects without PD." (PMID 35163551, 2022). "The lack of individuals developing parkinsonism (converters) in the cohort, prohibits a conclusive interpretation of UPSIT scores in subjects with GBA1 biallelic or heterozygous mutations but without PD." (PMID 36330429, 2022). "Furthermore, we detected the increased phosphorylation of α‐synuclein, a biomarker for Parkinson's disease, in DA neurons derived from a GD1 patient, which was significantly decreased by the overexpression of wild‐type GBA1." (PMID 33342090, 2021). "This study provides further longitudinal evidence of deteriorating olfaction, cognition, and motor signs and symptoms of parkinsonism among GBA1 carriers without PD." (PMID 31251436, 2019). "While lysosomal dysfunction and sphingolipids are implicated in the development of Parkinson’s disease in patients with Gaucher disease and their first-degree relatives, no clear mechanistic pathway for GBA1-related Parkinson’s disease and Lewy body dementia has yet been established." (PMID 41152894, 2025). "Several pathological mutations in the genes coding for PTEN-induced Kinase 1 (PINK1), Parkin, Leucine Rich Repeat Kinase 2 (LRRK2), glucocerebrosidase 1 (GBA1) and DJ-1 or PARK7 (Parkinson disease protein 7) were subsequently reported and established the genetic link to PD." (PMID 40540721, 2025).
lysosomal storage disorder (173 papers, 2006 to 2026). "Biallelic GBA1 mutations cause Gaucher disease (GD), a lysosomal storage disorder (LSD) characterized by impaired degradation of glucosylceramide and glucosylsphingosine, resulting in lipid accumulation within lysosomes." (PMID 41009720, 2025). "Gaucher disease (GD) is a rare autosomal recessive lysosomal storage disease caused by mutations in the glucocerebrosidase (GBA1) gene located on chromosome 1q21, leading to a deficiency in the enzyme β-glucocerebrosidase." (PMID 40137425, 2025). "In this study, we also analyzed the WES data for monogenic PD causes, lysosomal disorders and potential modifier genes that amplify the effect of the GBA1 gene." (PMID 40542290, 2025). "For Sample 29, this enzyme is responsible for the breakdown of glucocerebroside, and mutations in GBA1 are a common cause of Gaucher disease type 1, a lysosomal storage disorder." (PMID 40282387, 2025). "Gaucher’s disease (GD) is an autosomal recessive lysosomal storage disorder (LSD) due to mutations in GBA1, resulting in a deficiency of the enzyme glucocerebrosidase." (PMID 39912015, 2025). "Alterations in EV morphology were previously observed in our study of GD, a lysosomal storage disorder caused by biallelic mutations in the GBA1 gene." (PMID 41009720, 2025). "It is a lysosomal storage disorder caused by pathogenic biallelic variants in the GBA1 gene, which encodes the lysosomal enzyme acid beta-glucocerebrosidase." (PMID 38464899, 2024). "Gaucher disease, an autosomal recessively inherited lysosomal storage disorder, results from biallelic mutations in the GBA1 gene resulting in deficient activity of the enzyme glucocerebrosidase." (PMID 38540423, 2024). "Loss of function mutations in GBA1 leads to the accumulation of glucocerebroside, causing related lysosomal storage disease, while non lysosomal GBA2 can lead to the accumulation of GlcCer in various tissues outside the lysosome, such as the testes and liver." (PMID 39698091, 2024). "Bi-allelic mutations in the GBA1 gene have been known for decades to cause the commonest lysosomal storage disorder (LSD) GD." (PMID 38368939, 2024). "Gaucher disease (GD) is a lysosomal storage disorder (LSD) resulting from inherited glucocerebrosidase (GBA1) deficiency." (PMID 39395789, 2024). "Mutations in the gene for glucocerebrosidase (GBA1) are causative for the lysosomal storage disorder Gaucher Disease, but also represent a major risk factor to develop PD." (PMID 36715870, 2023). "Gaucher disease (GD) is a lysosomal storage disorder characterized by deficient glucocerebrosidase activity that results from biallelic mutations in the GBA1 gene." (PMID 37715271, 2023). "Gaucher disease (GD) is an autosomal recessive lysosomal storage disease resulting from deficiency of the β‐glucosidase (glucocerebrosidase) enzyme (GBA1 gene), which hydrolyzes glucosylceramide (Gb1) into glucose and ceramide." (PMID 36101816, 2022). "GBA encodes beta-glucocerebrosidase, and biallelic pathogenic variants of GBA1 cause Gaucher disease (GD), a lysosomal disorder." (PMID 35395825, 2022). "Many recent studies have revealed a relationship between lysosomal storage disorders and common neurodegenerative diseases, the most common example of which is the relationship between GBA1 mutations and PD." (PMID 35486332, 2022). "Biallelic mutations in GBA1, which encodes the lysosomal enzyme glucocerebrosidase, cause the lysosomal storage disorder Gaucher disease (GD)." (PMID 36330429, 2022). "Gaucher disease (GD) is a rare autosomal recessive lysosomal storage disorder caused by pathologic variants in GBA1, the gene encoding the enzyme glucocerebrosidase." (PMID 34234814, 2021). "Gaucher disease (GD) is a lysosomal storage disease caused by mutations in the glucocerebrosidase gene (GBA1) that leads to deficient lysosomal acid β-glucosidase (glucocerebrosidase, EC 3.2.1.21) activity." (PMID 33602299, 2021).